CDC20B (cell division cycle 20B)
Description:
Protein regulator of centriole-deuterosome disengagement and subsequently participates in the ciliogenesis in multiciliated cells (MCCs).
Synonyms: G6VTS76519; FLJ37927
Tractability: No criterion of Open Targets' tractability assessment is met for any kind of drug.
Gene: Protein-coding gene on chromosome 5 (55,112,971 to 55,173,177, reverse strand). Ensembl gene ENSG00000164287.
Subcellular location: Cytoplasm
Gene Ontology:
Molecular function: protein binding; anaphase-promoting complex binding; ubiquitin ligase activator activity; ubiquitin-protein transferase activator activity
Biological process: de novo centriole assembly; anaphase-promoting complex-dependent catabolic process; positive regulation of anaphase-promoting complex-dependent catabolic process
Cellular component: deuterosome; anaphase-promoting complex; cytoplasm
Genetic constraint (gnomAD): Loss-of-function variants: 42 observed, 43.46 expected, observed/expected ratio (o/e) 0.97, 90% interval 0.75 to 1.25. The upper end of that interval is the gene's LOEUF score, 1.25, which puts it in group 5 of 6, group 1 being the genes least tolerant of losing a copy. Missense variants: 431 observed, 478.69 expected, observed/expected ratio (o/e) 0.9, 90% interval 0.83 to 0.98. Synonymous variants: 186 observed, 180.54 expected, observed/expected ratio (o/e) 1.03, 90% interval 0.91 to 1.16.
Homologues: Orthologues: chimpanzee CDC20B (98% identical), macaque CDC20B (94% identical), pig CDC20B (81% identical), guinea pig CDC20B (77% identical), rabbit CDC20B (76% identical), mouse Cdc20b (72% identical), dog CDC20B (72% identical), tropical clawed frog cdc20b (47% identical), Drosophila melanogaster fzy (28% identical). Paralogues in human: CDC20 (33% identical), FZR1 (25% identical).
Diseases named in the same sentence as CDC20B in open-access papers:
CDC20B is named in the same sentence as 10 diseases in open-access papers, as found by Europe PMC text mining. Sharing a sentence is not in itself a finding about the gene and the disease. The quoted sentences say what the papers report.
atherosclerosis (1 paper, 2022). A disease characterized by the build-up of fatty material and calcium deposition in the arterial wall resulting in partial or complete occlusion of the arterial lumen. "Taken together, hsa_circ_0008896 regulated the expression of CDC20B by sponging hsa-miR-633, and then enhanced proliferation, migration, and invasion of VSMCs to promote the progression of atherosclerosis." (PMID 35212610, 2022). "Hsa_circ_0008896, which was highly expressed in both in vitro and in vivo atherosclerosis, increased the expression of CDC20B via binding to hsa-miR-633." (PMID 35212610, 2022). "In this study, we demonstrated that hsa_circ_0008896 regulated the hsa-miR-633/CDC20B axis to enhance proliferation, migration, and invasion of VSMCs, contributing to the progression of atherosclerosis." (PMID 35212610, 2022). "The regulated target of hsa-circ_0008896, CDC20B, participates in the nuclear movement prior to anaphase in the cell cycle, indicating that cell cycle associated proteins may be key players in regulating the proliferation of VSMCs in the pathological process of atherosclerosis." (PMID 35212610, 2022). "We detected the expression level of CDC20B in the cellular model of atherosclerosis, and results showed CDC20B was up-regulated in VSMCs treated with ox-LDL, indicating CDC20B expression level was regulated by hsa-circ_0008896." (PMID 35212610, 2022). "Here, we reported that hsa_circ_0008896 was up-regulated in the atherosclerosis cellular and mice models, and hsa_circ_0008896 increased the expression of CDC20B by competitively binding to hsa-miR-633 to increase the proliferation, migration and invasion of VSMCs." (PMID 35212610, 2022). "Firstly, we examined the CDC20B level in our cellular atherosclerosis model stimulated with ox-LDL, and found that CDC20B expression increased in the cellular atherosclerosis model." (PMID 35212610, 2022).
breast carcinoma (1 paper, 2023). "Therefore, we hypothesize the role of CDC20B in acquired non-steroidal AI resistance in breast cancer patients." (PMID 37415453, 2023). "Further in vitro and in vivo studies are required to support the involvement of CDC20B, HSD3B1, and CDKN2A, as possible prognostic biomarkers of non-steroidal AI resistance in breast cancer." (PMID 37415453, 2023).
lung carcinoma (1 paper, 2013). "MiR-449a is located in the first intron of CDC20B on chromosome 5q11 which is often a site of abnormality in lung cancer." (PMID 23734217, 2013).
ovarian carcinoma (1 paper, 2022). A malignant neoplasm originating from the surface ovarian epithelium. "Recently, high expression of CDC20B was found to be associated with a low survival rate of ovarian cancer, suggesting that CDC20B might be an oncogene regulating the proliferation of cancer cells." (PMID 35212610, 2022).
cancer (5 papers, 2016 to 2024). A tumor composed of atypical neoplastic, often pleomorphic cells that invade other tissues. "The miR-449 family consists of three members (miR-449a, miR-449b, and miR-449c) encoded by a cluster located on chromosome 5q11.2 in CDC20B, which has been associated with cancer susceptibility." (PMID 36545680, 2022). "MiR-449 family consists of three members (miR-449a, miR-449b, and miR-449c) encoded by a cluster located on chromosome 5q11.2 in the second intron of CDC20B, identified as a susceptibility region in cancer." (PMID 33396625, 2020). "CDC20B, DCTN3, CEP295 and TIMLESS were shown to promote cell cycle progression and be associated with tumor progression in many types of cancer." (PMID 39527598, 2024). "As expected, quantitative real-time PCR (qRT-PCR) revealed that CDC20B was concordantly overexpressed in the three miR-449a overexpressing cancer lines." (PMID 26934316, 2016).
infection (1 paper, 2021). The state of being infected such as from the introduction of a foreign agent such as serum, vaccine, antigenic substance or organism. "Numerous CDC genes are differentially expressed in the lung tissue of mice recovering from an acute PVM infection, including Cdc20, Cdc20b, Cdca3, Cdca4, and Cdca7." (PMID 34959580, 2021).
CDC20B also shares sentences with these, for which no sentence is quoted: tumor (2 papers); Azoospermia (1); liver cancer (1); lymphoma (1).